MRE11 (MRE11 double strand break repair nuclease)
Description:
Core component of the MRN complex, which plays a central role in double-strand break (DSB) repair, DNA recombination, maintenance of telomere integrity and meiosis. The MRN complex is involved in the repair of DNA double-strand breaks (DSBs) via homologous recombination (HR), an error-free mechanism which primarily occurs during S and G2 phases. The complex (1) mediates the end resection of damaged DNA, which generates proper single-stranded DNA, a key initial steps in HR, and is (2) required for the recruitment of other repair factors and efficient activation of ATM and ATR upon DNA damage. Within the MRN complex, MRE11 possesses both single-strand endonuclease activity and double-strand-specific 3'-5' exonuclease activity. After DSBs, MRE11 is loaded onto DSBs sites and cleaves DNA by cooperating with RBBP8/CtIP to initiate end resection. MRE11 first endonucleolytically cleaves the 5' strand at DNA DSB ends to prevent non-homologous end joining (NHEJ) and licence HR. It then generates a single-stranded DNA gap via 3' to 5' exonucleolytic degradation to create entry sites for EXO1- and DNA2-mediated 5' to 3' long-range resection, which is required for single-strand invasion and recombination. RBBP8/CtIP specifically promotes the endonuclease activity of MRE11 to clear protein-DNA adducts and generate clean double-strand break ends. MRE11 endonuclease activity is also enhanced by AGER/RAGE (By similarity). The MRN complex is also required for DNA damage signaling via activation of the ATM and ATR kinases: the nuclease activity of MRE11 is not required to activate ATM and ATR. The MRN complex is also required for the processing of R-loops. The MRN complex is involved in the activation of the cGAS-STING pathway induced by DNA damage during tumorigenesis: the MRN complex acts by displacing CGAS from nucleosome sequestration, thereby activating it (By similarity). In telomeres the MRN complex may modulate t-loop formation. MRE11 contains two DNA-binding domains (DBDs), enabling it to bind both single-stranded DNA (ssDNA) and double-stranded DNA (dsDNA).
Synonyms: HNGS1; MRE11A; ATLD; MRE11B
Tractability: Small molecule: it has a high-quality binding pocket. PROTAC: UniProt records ubiquitination sites on it; ubiquitination databases record sites on it.
Target class: Enzyme; Hydrolase
Gene: Protein-coding gene on chromosome 11 (94,415,570 to 94,493,889, reverse strand). Ensembl gene ENSG00000020922.
Subcellular location: Nucleus; Chromosome; Chromosome, telomere
Subcellular location (Human Protein Atlas): Nucleoplasm
Pathways (Reactome):
DNA Repair: HDR through Homologous Recombination (HRR); HDR through MMEJ (alt-NHEJ); HDR through Single Strand Annealing (SSA); Homologous DNA Pairing and Strand Exchange; Nonhomologous End-Joining (NHEJ); Presynaptic phase of homologous DNA pairing and strand exchange; Processing of DNA double-strand break ends; Recruitment and ATM-mediated phosphorylation of repair and signaling proteins at DNA double strand breaks; Resolution of D-loop Structures through Holliday Junction Intermediates; Resolution of D-loop Structures through Synthesis-Dependent Strand Annealing (SDSA); Sensing of DNA Double Strand Breaks
Disease: Defective HDR through Homologous Recombination Repair (HRR) due to PALB2 loss of BRCA1 binding function; Defective HDR through Homologous Recombination Repair (HRR) due to PALB2 loss of BRCA2/RAD51/RAD51C binding function; Defective homologous recombination repair (HRR) due to BRCA1 loss of function; Impaired BRCA2 binding to PALB2; Impaired BRCA2 binding to RAD51
Immune System: Cytosolic sensors of pathogen-associated DNA; IRF3-mediated induction of type I IFN
Cell Cycle: G2/M DNA damage checkpoint
Cellular responses to stimuli: DNA Damage/Telomere Stress Induced Senescence
Reproduction: Meiotic recombination
Gene Ontology:
Molecular function: 3'-5' exonuclease activity; 3'-5'-DNA exonuclease activity; cadherin binding; DNA binding; DNA endonuclease activity; DNA helicase activity; identical protein binding; protein binding; single-stranded DNA endodeoxyribonuclease activity; double-stranded DNA binding; nuclease activity; endonuclease activity; hydrolase activity; manganese ion binding
Biological process: DNA damage response; DNA double-strand break processing; DNA strand resection involved in replication fork processing; double-strand break repair; double-strand break repair via homologous recombination; double-strand break repair via nonhomologous end joining; negative regulation of apoptotic process; negative regulation of double-strand break repair via nonhomologous end joining; positive regulation of double-strand break repair; positive regulation of telomere maintenance; R-loop processing; sister chromatid cohesion; telomeric 3' overhang formation; DNA recombination; DNA repair; homologous recombination; meiotic DNA double-strand break formation; mitochondrial double-strand break repair via homologous recombination; mitotic G2 DNA damage checkpoint signaling; mitotic G2/M transition checkpoint; mitotic intra-S DNA damage checkpoint signaling; reciprocal meiotic recombination; regulation of mitotic recombination; telomere maintenance; telomere maintenance via telomerase
Cellular component: BRCA1-C complex; chromosome; chromosome, telomeric region; cytoplasm; Mre11 complex; nucleoplasm; nucleus; PML body; replication fork; site of double-strand break; chromosomal region; cytosol
Genetic constraint (gnomAD): Loss-of-function variants: 49 observed, 77.61 expected, observed/expected ratio (o/e) 0.63, 90% interval 0.5 to 0.8. The upper end of that interval is the gene's LOEUF score, 0.8, which puts it in group 3 of 6, group 1 being the genes least tolerant of losing a copy. Missense variants: 707 observed, 791 expected, observed/expected ratio (o/e) 0.89, 90% interval 0.84 to 0.95. Synonymous variants: 247 observed, 258.77 expected, observed/expected ratio (o/e) 0.95, 90% interval 0.86 to 1.06.
Gene-disease validity (ClinGen):
ClinGen rates the evidence that MRE11 causes each of these diseases.
familial ovarian cancer (autosomal dominant): Refuted. An instance of ovarian cancer that is caused by an inherited modification of the individual's genome.
hereditary breast carcinoma (autosomal dominant): Refuted. Breast carcinoma that has developed in relatives of patients with history of breast carcinoma.
Homologues: Orthologues: chimpanzee MRE11 (99% identical), macaque MRE11 (97% identical), dog MRE11 (94% identical), guinea pig MRE11 (90% identical), rabbit MRE11 (90% identical), rat Mre11 (89% identical), mouse Mre11a (88% identical), pig MRE11 (83% identical), tropical clawed frog mre11 (74% identical), zebrafish mre11a (63% identical), Drosophila melanogaster mre11 (37% identical), Caenorhabditis elegans mre-11 (34% identical).
Diseases named in the same sentence as MRE11 in open-access papers:
MRE11 is named in the same sentence as 131 diseases in open-access papers, as found by Europe PMC text mining. Sharing a sentence is not in itself a finding about the gene and the disease. The quoted sentences say what the papers report.
breast carcinoma (62 papers, 2005 to 2025). "This is supported by the fact that overexpression of DNA2 blocks the MRE11-mediated fork degradation in Brca2-deficient mouse mammary tumor cells." (PMID 38271119, 2024). "High MRE11 expression has been implicated with poor prognosis and chemoresistance in gastric cancer, colon cancer, breast cancer as well as glioma." (PMID 36213114, 2022). "Low nuclear MRE11 was significantly associated with poor breast cancer-specific survival (BCSS) (p = 0.002)." (PMID 34782604, 2021). "MRE11 protein expression is also associated with the prognosis and development of human cancers, such as bladder cancer, colon cancer, and breast cancer." (PMID 31221177, 2019). "In this case-control study, we investigated the relationships between other variants in ATM, H2AFX and MRE11 genes and risk of breast cancer." (PMID 29678143, 2018). "An intact MRN complex predicts a good response to treatment in patients with early breast cancer, whereas mutations in MRE11, NBS1, or RAD50 have been linked to increased risk of cancer, including sporadic and familial cancers." (PMID 29189711, 2017). "Our previous work using similar statistical methods revealed that MRE11 is associated with breast cancer malignancy." (PMID 28133604, 2017). "We have also previously identified two germline mutations in the MRE11 gene among breast cancer patients whose tumors showed decreased expression of the MRN complex proteins MRE11, RAD50, and NBS1 that play an important role in the DNA damage response." (PMID 25918678, 2015). "We observed lower MRE11 expression in tumour cells than normal urothelium in breast tumours; low MRE11 was associated with poorer radiotherapy outcomes in breast cancer." (PMID 24625413, 2014). "al has excluded any association of the RAD50/MRE11 polymorphisms and breast cancer risk, beside one SNP in NBN." (PMID 24079363, 2013). "Germline mutations in NBS1, RAD50, and MRE11 genes, although seen in low frequencies and can be population specific, can be qualified as novel candidates for breast cancer susceptibility in a subset of non-BRCA1 and BRCA/2 families." (PMID 23586058, 2013). "In this study, we hypothesize a role of variants in the ATM, H2AFX and MRE11 genes in determining breast cancer (BC) susceptibility." (PMID 29678143, 2018). "We hypothesize that variants in the ATM, H2AFX and MRE11 genes may modulate a predisposition to breast cancer." (PMID 29678143, 2018). "Similarly, in breast cancer high MRE11 expression was associated with a more malignant behavior of the disease, lymph node metastasis, and higher recurrence rates after radiotherapy and chemotherapy, whereas low DKC1 expression and activity were related to a better prognosis." (PMID 26366868, 2015). "In basal-like breast cancer, MRE11 K673la improves DNA end resection and homologous recombination repair, conferring resistance to poly ADP-ribose polymerase inhibitors, olaparib, and cisplatin." (PMID 40994548, 2025). "Reverse-phase protein array (RPPA) analysis from TCGA breast cancer data set also showed reduced MRE11 protein expression in DNA2-low samples." (PMID 38271119, 2024).
breast carcinoma (continued). "FANCD2 is highly overexpressed in BRCA1/2 mutant breast cancers and contributes to DNA fork stability by inhibiting MRE11-mediated DNA replication fork degradation in BRCA1/2 mutant breast cancer cells." (PMID 37892162, 2023). "In human breast cancer cells, MRE11 regulates cell proliferation via signal transducer and activator of transcription 3 (STAT3)." (PMID 36147632, 2022). "MRE11 is engaged in DNA damage repair pathways, and it was previously reported to be involved in the breast cancer progression, and played a role in the response of drug treatment in glioma." (PMID 35044082, 2022). "The risk score was positively related to some known molecules (MDR1, Twist, HIF, MRE11, FR1) associated with chemotherapy resistance in breast cancer (Xiwei 32)." (PMID 36341435, 2022). "The hazard ratio of other six genes (FAAP20, RRM2B, UBE2A,RAD50,MRE11, and RPA3) was >1, regarded as risk factors in developing breast cancer." (PMID 36713553, 2022). "In general, the normal fibroblasts showed quicker phosphorylation of H2AX and recruitment of MRE11 to γH2AX clusters compared to breast cancer cells and a shorter time interval of increased similarity for γH2AX clusters." (PMID 34771723, 2021). "Mre11 expression was upregulated in lung and liver cancers, but not in kidney, prostate, and uterus cancers, and was significantly downregulated in breast cancer." (PMID 32111912, 2020). "Previous studies have shown that MRE11 overexpression in breast cancer cells leads to cell proliferation by stimulating STAT3 signalling and enhances migration and invasion capabilities through activation of MMP-2 and MMP-9." (PMID 31221177, 2019). "We analyzed the spatial arrangements of antibody-labelled MRE11 proteins in the nuclei of a breast cancer and a skin fibroblast cell line along a time-course of repair (up to 48 h) after irradiation with a dose of 2 Gy." (PMID 29361783, 2018). "Together, these results suggest that cyclin A2 is a positive regulator of MRE11 in breast cancer cells." (PMID 29207607, 2017). "We demonstrate that cyclin A2 plays a vital role in maintaining adequate levels of MRE11 and RAD51 proteins for proper functioning of HR repair and that its loss sensitizes the breast cancer cells to DNA damaging agents and PARP inhibitors." (PMID 29207607, 2017). "Our previous study reported the important role of meiotic recombination 11 homolog A (MRE11) in cell proliferation, tumor invasion, and DNA repair in patients with breast cancer." (PMID 28133604, 2017). "The MRE11 is considered an oncoprotein because it is overexpressed in colorectal cancer and in highly malignant breast cancer." (PMID 28133604, 2017). "Lowered expression of Rad50 and Mre11, both of which are key components of the MRN complex and linked to increased breast cancer susceptibility, was also identified." (PMID 27014724, 2016). "PARP-1 can also recruit protein MRE11, ATM (ataxiatel angiectasia mutated) to suppress the transcription factors E2F4 and P130 complexes and impact the expression of breast cancer susceptibility genes BRCA1 and RAD5, which transiently protects the DNA gaps and inhibits recombinant." (PMID 36590386, 2022). "In total, 11 DNA repair genes (UBE2A, RBBP8,RAD50, FAAP20, RPA3, ENDOV, DDB2, UBE2V2,MRE11, RRM2B, andPARP3) were preserved as prognostic genes to estimate risk score, which was applied to establish the prognostic model and stratified breast cancer patients into two groups with high or low risk." (PMID 36713553, 2022). "MRE11 promotes cell proliferation, tumour invasion and DNA repair in breast cancer." (PMID 34734468, 2021). "We observed nuclear and cytoplasmic MRE11 expression in breast cancers." (PMID 34782604, 2021). "In conclusion, MRE11 clusters show similar behavior in fibroblasts and breast cancer cells." (PMID 34771723, 2021).
breast carcinoma (continued). "In a mice model of sporadic onco-gene-driven breast tumorigenesis, impairment of the functions of Mre11 complex promotes the progression of mammary hyperplasia into invasive, metastatic breast cancer while intact Mre11–mediated DDR restrains progression of mammary hyperplasia." (PMID 31767017, 2019). "MRE11A is part of the DNA double-strand break repair MRE11/RAD50/NBS1 complex that is required for non-homologous joining of DNA ends which associates with breast cancer risk." (PMID 30370249, 2018). "In the following, we will show analyses of the protein MRE11 arrangement in nuclei of two different cell lines (breast cancer cell line MCF-7, skin fibroblast cell line CCD-1059SK) after low LET irradiation with a dose of 2 Gy and during a time course of repair of up to 48 h." (PMID 29361783, 2018). "In this report, there is a lack of association of MRE11 polymorphisms with breast cancer patients from Poland." (PMID 29678143, 2018). "Furthermore, MRE11 has been shown to function as a barrier to tumourigenesis, and inherited heterozygous mutations in MRE11, NBS1 or RAD50 are associated with a low-intermediate penetrance risk of breast cancer." (PMID 27335639, 2016). "Analyzing breast cancer patients' tumours can lead to the identification of MRE11 germline mutations based on the reduced or lack of expression of all three (MRN) proteins." (PMID 23586058, 2013). "Moreover, in breast cancer, MRE11 overexpression promotes proliferation by activation of the STAT3 signaling and its downstream effectors on one side, and tumor cell invasion and migration by an increase in secretion of metastasis-associated MMP proteins (MMP-2 and MMP-9), on the other side." (PMID 37509263, 2023). "In the current study, we did not observe similar involvement of STAT3 in oral cancer, suggesting that cell type differences between oral cancer (squamous cell carcinoma) and breast cancer (adenocarcinoma) may contribute to differences in the MRE11-preferential signaling pathways." (PMID 33927349, 2021). "By applying the CIPHER-HIT to the subtype analysis of Breast cancer, we found that the prioritized genes can be divided into two sub-modules, one contains the members of the Fanconi anemia gene family, and the other contains a reported protein complex MRE11/RAD50/NBN." (PMID 21599985, 2011). "For some genes, single P/LP variants were detected either only in the group of patients with breast cancer (APC, MDM1, MRE11, POLD1, NF1, RAD51C, RECQL4, and WRN) or only in the control group (MCPH1, MSH3, and XPC)." (PMID 39684352, 2024). "In a panel of breast cancer lines (MCF7, MDA-MB-231, MDA-MB-436, SKBR-3, MDA-MB-175VII), we also evaluated Mre11 at baseline and after cisplatin treatment." (PMID 35853939, 2022). "A total of 11 DNA repair genes, namely, UBE2A, RBBP8,RAD50, FAAP20, RPA3, ENDOV, DDB2, UBE2V2,MRE11, RRM2B, andPARP3, were involved in the prognostic model for breast cancer patients." (PMID 36713553, 2022). "In another study of MRN expression in breast cancers, the authors reported reduced RAD50 (3%), MRE11 (7%) and NBS1 (10%) protein expression, particularly in triple-negative disease, high-grade tumours and in familial breast cancers." (PMID 34782604, 2021). "RNA-sequencing data were obtained from primary female breast cancer specimens (n = 1080) from the TGCA breast cancer project and was stratified on the basis of quartile expression of MRE11, RAD50 and NBS1 and differentially expressed genes (DEGs) identified." (PMID 34782604, 2021). "We initially tested MRE11, RAD50 and NBS1 protein expression in a panel of breast cancer cell lines [MCF-7 (ER+, luminal A), ZR-75-1 (ER+, luminal B), SKBR3 (HER2+), MDA-MB-231 (triple-negative)]." (PMID 34782604, 2021). "Rsk and Plk1 both suppress DNA-damage checkpoint signaling by phosphorylating and inhibiting MRE11 activity, whilst FGFR2 regulates MRE11 expression through the MEK/ERK/POU1F1 pathway in breast cancer." (PMID 33927349, 2021).